MT-TL1 (mitochondrially encoded tRNA-Leu (UUA/G) 1)
Synonyms: TRNL1; formerly MTTL1
Gene: Mitochondrial transfer RNA gene on chromosome MT (3,230 to 3,304, forward strand). Ensembl gene ENSG00000209082.
Gene Ontology:
Molecular function: triplet codon-amino acid adaptor activity
Biological process: translation
Gene-disease validity (ClinGen):
ClinGen rates the evidence that MT-TL1 causes each of these diseases.
mitochondrial disease (mitochondrial): Definitive.
Leigh syndrome (mitochondrial): Limited. A progressive neurological disease defined by specific neuropathological features associating brainstem and basal ganglia lesions.
Diseases named in the same sentence as MT-TL1 in open-access papers:
MT-TL1 is named in the same sentence as 36 diseases in open-access papers, as found by Europe PMC text mining. Sharing a sentence is not in itself a finding about the gene and the disease. The quoted sentences say what the papers report.
MELAS (21 papers, 2012 to 2025). "Cardiac involvement in MELAS syndrome harboring the MTTL1 m.3243A > G mutation mostly entails cardiomyopathy, which was particularly evident in the cardiac MRI." (PMID 39930534, 2025). "In about four out of five patients, MELAS syndrome is connected with a point mutation in the MTTL1 gene that encodes tRNA-Leu (m.3243A>G)." (PMID 35163523, 2022). "MELAS syndrome due to MTTL1 A3243G mutation was the most frequent finding (9%), followed by TMEM70 (6%), NARP and Barth syndrome (5% each)." (PMID 32736646, 2020). "The gene for mt-tRNALeu(UUR), MTTL1, is widely acknowledged as a hotspot for mitochondrial disease-causing point mutations and is most commonly associated with the MELAS syndrome." (PMID 23273904, 2013). "MELAS syndrome is associated in about 80% of cases with a mutation at position 3243 in the mitochondrial gene MTTL1 (MIM ID *590050), encoding mitochondrial tRNA leucine 1(3243A > G transition), although other mutations have also been described." (PMID 22353239, 2012). "Therefore, an in-depth analysis of the cardiac involvement of patients with MELAS syndrome and the MTTL1 m.3243A > G mutation is necessary." (PMID 39930534, 2025). "Cox proportional hazards regression analysis was used to examine potential risk factors associated with diabetes onset in MELAS patients with MTTL1 mutations." (PMID 40382647, 2025). "To further investigate factors influencing the onset of DM in MELAS patients with MTTL1 mutations, we assessed associated risk factors during the follow-up period." (PMID 40382647, 2025). "In the current prospective study, cardiac involvement was found in nine of 11 MELAS patients (82%) with the MTTL1 m.3243A > G mutation." (PMID 39930534, 2025). "MELAS is most often caused by a 3243A-G transition in the MTTL1 gene; MERFF is caused in up to 90% of cases by an A-G mutation at nucleotide 8344 of the MTTK gene." (PMID 36862146, 2023). "Other individuals that are diagnosed with a MELAS have other variants of MTTL1 or mutations in some other mitochondrial genes." (PMID 35163523, 2022). "Another infant was detected as a heteroplasmic of a pathogenic variant (m.3244A>G) in MTTL1, which suggested the risk of mitochondrial encephalomyopathy with lactic acidemia and stroke-like episodes (MELAS)." (PMID 34794485, 2021). "In approximately 80% of MELAS patients, the causative mutation is the m.3243A>G pathogenic variant in MTTL1 (mt-tRNALeu)." (PMID 33426504, 2020). "We report a MELAS case with a rare heteroplasmic m.3243A>T mutation found by direct sequencing of MTTL1." (PMID 30210801, 2018). "A heteroplasmic m.3291T>C variant in the MTTL1 gene has previously been reported on 4 separate occasions, in association with MELAS, isolated mild myopathy, dementia with hearing loss and cerebellar ataxia with ophthalmoparesis, hearing loss and myopathy." (PMID 23273904, 2013). "Molecular genetic testing identified the most common mutation found in MELAS patients, MTTL1 (MIM ID *590050), encoding mitochondrial tRNA leucine 1(3243A > G transition)." (PMID 22353239, 2012). "Our study highlights distinct patterns of diabetes onset in MELAS patients with MTTL1 mutations." (PMID 40382647, 2025). "In addition to the classic MTTL1 m.3243A > G mutation a variety of other mitochondrial DNA mutations have been associated with MELAS." (PMID 38156086, 2023). "For example, about 80% of patients with MELAS harbor the m.3243A>G mutation in the mitochondrial tRNALeu(UUR) gene (MTTL1), whereas mutations in polypeptide-coding genes, including subunits 1, 5, and 6 of complex I (MT-ND1, MT-ND5, and MT-ND6), have also been identified in MELAS." (PMID 34025555, 2021). "MT-TL1 is one of the most common pathogenic mitochondrial gene mutations, and is a genetic cause of mitochondrial encephalomyopathy with lactic acidosis and stroke-like episodes (MELAS)." (PMID 31653782, 2019).
MELAS (continued). "In addition, one individual demonstrated heteroplasmy for MTTL1 3243 A > G (estimated 58% frequency in blood) which is the most common mtDNA mutation associated with Mitochondrial Encephalomyopathy, Lactic Acidosis, and Stroke-like episodes (MELAS, MIM 540000)." (PMID 34531397, 2021). "In the 30 symptomatic non-MELAS patients, all except 2 had confirmatory genetic testing with the classic MTTL1 m.3242A > G mutation; of the two who did not, one had m.13513G > A in ND5 gene and had MIDD phenotype and the other had biopsy confirmation and had encephalopathy without SLE." (PMID 38156086, 2023). "It is most commonly associated with MTTL1 m.3243A > G mutation in mitochondrial DNA, however, there are many individuals who carry this mutation who remain asymptomatic or do not meet clinical criteria for MELAS." (PMID 38156086, 2023). "Moreover, in many mitochondrial or inherited muscle diseases, genetic mutations are not pathognomonic, such as the m.3245A>G mutation in the MT-TL1 gene in MELAS (found in 80% of patients), and not systematically associated with the pathology while being carried by 1/400 white Europeans." (PMID 35565853, 2022).
mitochondrial encephalomyopathy (5 papers, 2016 to 2026). A heterogenous group of disorders characterized by alterations of mitochondrial metabolism that result in muscle and nervous system dysfunction. "Laboratory tests demonstrated elevated serum lactate, HbA1c, and high-sensitivity cardiac troponin T. Targeted sequencing identified a pathogenic m.3243A > G variant in the MT-TL1 gene with 55.6% heteroplasmy, confirming mitochondrial encephalomyopathy with cardiac involvement." (PMID 42079699, 2026).
lactic acidosis (4 papers, 2016 to 2024). Metabolic acidosis characterized by the accumulation of lactate in the body. "Mitochondrial encephalopathy with lactic acidosis and stroke-like episodes is most commonly secondary to a transfer RNA (tRNA) variation caused by a mutation in the MTTL1 mitochondrial gene." (PMID 39583497, 2024).
cardiomyopathy (3 papers, 2014 to 2025). A disease of the heart muscle or myocardium proper. "Thirteen patients from 10 families with cardiomyopathy harbored three different mutations as follows: MTTK m.8363G > A (one family), MTND1 m.3943G > A (one family), and MTTL1 m.3243 A > G mutations (eight families)." (PMID 40382647, 2025).
diabetes (3 papers, 2014 to 2025). "Diabetes in Cocker Spaniels showed an association with three SNPs from three different genes: MTTL1 (rs24305581), PAX4 (rs22302353) and INS (rs22686871) and in the miniature Dachshund there was a single association with HNF4A (rs8804236)." (PMID 26401325, 2014).
deafness (2 papers, 2021 to 2023). An inherited or acquired condition characterized by the complete loss of the ability to hear from one or both ears. "Three patients with m.3243A > G mutation in MTTL1 were diagnosed with maternally inherited diabetes and deafness with a hemoglobin A1c (HbA1c) level of 8.2 ± 2.8% without β-cell autoantibodies." (PMID 33663443, 2021).
hearing loss (1 paper, 2023). "MT-RNR1 and MTTL1 variants lead to mitochondrial hearing loss, which has variable penetrance and severity, even within families." (PMID 36847978, 2023).
hypoparathyroidism (1 paper, 2025). Hypoparathyroidism is an endocrine disorder in which the parathyroid glands in the neck do not produce enough parathyroid hormone (PTH). "The patient with hypoparathyroidism also had the MTTL1 m.3243 A > G mutation." (PMID 40382647, 2025).
intestinal pseudo-obstruction (1 paper, 2016). A type of ILEUS, a functional not mechanical obstruction of the INTESTINES. "The m.3243A>G MTTL1 mutation is the most common cause of mitochondrial disease; yet there is limited awareness of intestinal pseudo‐obstruction (IPO) in this disorder." (PMID 27453452, 2016).
Mitochondrial myopathy (1 paper, 2020). "We performed an open‐label observational experimental medicine study of six patients with mitochondrial myopathy caused by the m.3243A>G MTTL1 mutation." (PMID 32107855, 2020). "We studied six unrelated adults with mitochondrial myopathy due to the m.3243A>G MTTL1 mutation in skeletal muscle (50–84% heteroplasmy, four female, mean age 50 years, range 44–57), identified from local clinics and the UK MRC Mitochondrial Disease Cohort." (PMID 32107855, 2020).
myoclonic epilepsy (1 paper, 2020). A group of epilepsy syndromes in which myoclonic seizures are a prominent feature. "Subsequently, came over others like MTTL1 and MTTK to be linked to LS: m.3243A > G MTTL1 responsible for MELAS and m.8344A > G MTTK related to Myoclonic Epilepsy with Ragged Red Fibers (MERRF)." (PMID 31996241, 2020).
Nephropathy (1 paper, 2025). A nonspecific term referring to disease or damage of the kidneys. "All nine patients with nephropathy had the MTTL1 m.3243 A > G mutations." (PMID 40382647, 2025).
papillary thyroid cancer (1 paper, 2025). "All five patients with papillary thyroid cancer harbored the MTTL1 m.3243 A > G mutation." (PMID 40382647, 2025).
cancer (2 papers, 2025). A tumor composed of atypical neoplastic, often pleomorphic cells that invade other tissues. "The MT-TL1 gene is part of the mitochondrial genome and has been linked to metabolic regulation and energy production in cancer cells." (PMID 40725410, 2025).
tumor (1 paper, 2025). "Several of these genes, such as CMTR1, play critical roles in mRNA cap methylation and immune response regulation, while GMPR and MT-TL1 are involved in metabolic pathways essential for tumor growth." (PMID 40725410, 2025).
MT-TL1 also shares sentences with these, for which no sentence is quoted: mitochondrial disease (5 papers); MELAS syndrome (4); Stroke (4); maternally inherited deafness and diabetes (2); Mitochondrial encephalopathy (2); atrial fibrillation (1); Barth syndrome (1); chronic progressive external ophthalmoplegia (1); dementia (1); Encephalopathy (1); familial hemiplegic migraine (1); glioma (1); ischemic encephalopathies (1); macular dystrophies (1); MERRF (1); migraine (1); monogenic diabetes (1); myopathy (1); Pearson syndrome (1); peripheral neuropathy (1); Retinopathy (1).